NSUN2 (NOP2/Sun RNA methyltransferase 2)
Diseases named in the same sentence as NSUN2 in open-access papers (continued):
Sharing a sentence is not in itself a finding about the gene and the disease.
retinoblastoma (7 papers, 2023 to 2026). A malignant tumor that originates in the nuclear layer of the retina. "NSUN2 is upregulated in retinoblastoma and associated with poorer survival rates." (PMID 41462962, 2025). "NSUN2-mediated m5C RNA methylation promoted purine biosynthesis in the oncogenic process of retinoblastoma." (PMID 41462962, 2025). "In summary, the carcinogenic cascade reaction of NSUN2–ALYREF–m5C–PFAS is an important triggering factor for retinoblastoma." (PMID 41462962, 2025). "In retinoblastoma (RB), the NSUN2/ALYREF/m5C-PFAS carcinogenic cascade is an important trigger of RB and can promote purine synthesis during the pathological process." (PMID 38764010, 2024). "Silencing NSUN2 prevented the malignant behavior of retinoblastoma cells." (PMID 41462962, 2025). "Downregulating NSUN2 inhibited glycolysis in retinoblastoma cells." (PMID 41462962, 2025). "In retinoblastoma (RB), NSUN2 depletion impairs glycolysis by reducing the stability of HKDC1 mRNA, which is dependent on its m5C modification." (PMID 41522342, 2026). "Furthermore, NSUN2 expression was elevated in retinoblastoma samples and cell lines." (PMID 41462962, 2025). "Mechanistically, NSUN2 and YBX1 promoted the malignant behavior and in vitro glycolysis of retinoblastoma through HKDC1, and accelerated tumor growth in vivo." (PMID 41462962, 2025). "In retinoblastoma studies, NSUN2 and YBX1 mediated the m5C modification and mRNA stability of HKDC1, where the global and mRNA m5C levels of retinoblastoma were significantly higher than those of normal retina." (PMID 41462962, 2025).
systemic lupus erythematosus (7 papers, 2022 to 2024). An autoimmune multi-organ disease typically associated with vasculopathy and autoantibody production. "In patients with systemic lupus erythematosus (SLE), the levels of m5C and the expression of NSUN2 are reduced in CD4+ T cells." (PMID 39726589, 2024). "In patients with Systemic lupus erythematosus (SLE), the levels of m5C and NSUN2 expression are decreased in CD4+ T cells, and hypermethylated m5C is involved in immune-related and inflammatory pathways, including the immune system, cytokine signaling, and interferon (IFN) signaling." (PMID 38902779, 2024). "Downregulated NSUN2 expression, along with decreased mRNA m5C levels of CD4+ T cells, was observed in systemic lupus erythematosus (SLE) patients, while the number of m5C-containing RNAs increased." (PMID 37325635, 2023). "One recent study has shown that Nsun2 expression and m5C levels were downregulated in CD4+ T cells from patients with systemic lupus erythematosus (SLE), however, upregulated genes with hypermethylated m5C were shown to disrupt immune system and promote the flares and remission of SLE patients." (PMID 36792629, 2023).
colon carcinoma (6 papers, 2020 to 2025). "It was reported that NSUN2 is highly expressed in colon cancers, which was corroborated in our results." (PMID 35281843, 2022). "For example, NSUN2 is involved in GRB2-mediated colon cancer cell migration." (PMID 40279954, 2025). "In addition to their original description of NSUN2 as an RNMT, Frye and Watt also observed high expression of NSUN2 in 3/4 colon cancers, an observation subsequently confirmed by other researchers." (PMID 32708015, 2020).
urothelial carcinoma of the bladder (6 papers, 2020 to 2025). "ALYREF recognizes hypermethylated m5C site of NSUN2, resulting in NSUN2 upregulation in urothelial carcinoma of the bladder (UCB)." (PMID 41462962, 2025). "Previous studies have shown that both ALYREF and NSUN2 are upregulated in urothelial carcinoma of the bladder, suggesting a possible synergistic effect." (PMID 41345330, 2025). "In human urothelial carcinoma of bladder, NSUN2 targets and regulates HDGF through m5C methylation, thereby promoting tumorigenesis." (PMID 33400376, 2021). "NSUN2 and YBX1 drive the pathogenesis of urothelial carcinoma of the bladder by targeting the m5C methylation site in the 3′-untranslated region of HDGF." (PMID 37398932, 2023). "A recent study showed that in human urothelial carcinoma of the bladder (UBC), NSUN2-mediated m5C modification stabilizes oncogene RNA through the “reader” YBX1, and hypermethylated m5C levels correlate with oncogene mRNA overexpression in UBC cells." (PMID 32978516, 2020).
uveal melanoma (6 papers, 2023 to 2025). A melanoma derived from melanocytes of the uveal tract. "Additionally, the NSUN2‐driven RNA m5C modification is linked to the modulation of uveal melanoma cell proliferation and motility." (PMID 40008496, 2025). "In uveal melanoma, NSUN2 participates in the m5C modification process and promotes the migration of uveal melanoma cells." (PMID 37769000, 2023). "Finally, NSUN2-mediated RNA m5C modification modulates uveal melanoma cell proliferation and migration, although the exact mechanisms remain unknown." (PMID 37325635, 2023). "Furthermore, NSUN2 was upregulated in both cellular and tissue specimens of uveal melanoma (UM), and β‐catenin (CTNNB1) was a direct target of NSUN2 action." (PMID 38572667, 2024).
acute myeloid leukemia (5 papers, 2025). Acute myeloid leukemia (AML) is a group of neoplasms arising from precursor cells committed to the myeloid cell-line differentiation. "In acute myeloid leukemia (AML), NSUN2 is aberrantly upregulated in patient samples and correlates with poor prognosis." (PMID 41256859, 2025). "NSUN2 also methylates mRNAs, where m5C stabilizes transcripts encoding key metabolic enzymes, including PHGDH and SHMT2, which are essential for serine/glycine biosynthesis and are implicated in acute myeloid leukemia (AML) progression and leukemic stem cell (LSC) self-renewal." (PMID 40973767, 2025). "In acute myeloid leukemia (AML), NSUN2 stabilizes PHGDH and SHMT2 mRNA and upregulates their expression by regulating m5C modification." (PMID 41462962, 2025). "In addition, by targeting the m5C modification mediated by NSUN2, the NSUN2 inhibitor MY-1B and the FSP1 inhibitor iFSP1 were able to significantly inhibit the survival of acute myeloid leukemia (AML) cells." (PMID 41180455, 2025).
liver cancer (5 papers, 2020 to 2026). An epithelial or non-epithelial malignant neoplasm that arises from the liver. "Recent studies have shown that NSUN2 deficiency suppresses proliferation and migration in HepG2 liver cancer cells." (PMID 40370440, 2025). "In liver cancer, the long non-coding RNA (lncRNA) H19 is a specific target of NSUN2." (PMID 40370440, 2025). "Among the genes associated with the prognosis of liver cancer, the genes associated with shorter survival period are AGO2, DCPS, IFIT5, LARP1, NCBP2, NUDT10, and NUDT16; the genes associated with longevity are EIF4E3, EIF4G3, METTL1, NCBP1, NSUN2, NUDT11, NUDT4, and WDR4." (PMID 36845384, 2023). "Further molecular mechanism analysis revealed that NSUN2 mediates m5C RNA modification of the SARS2 gene, which in turn activates the Wnt signaling pathway, promoting liver cancer progression." (PMID 40370440, 2025).
lymph node metastasis (5 papers, 2024 to 2025). "Elevated NSUN2 expression in multiple malignancies is correlated with lymph node metastasis, advanced clinical stage, and reduced overall survival." (PMID 40083919, 2025). "In addition, high numbers of NSUN2-expressing TAMs seemed to be related to lymph node metastasis and muscle invasion in patients." (PMID 41354740, 2025).
anaplastic thyroid cancer (4 papers, 2023 to 2025). "m5C methyltransferase NSUN2 catalyzes tRNA m5C modification, promoting the anaplastic thyroid cancer progression." (PMID 38468490, 2024). "In anaplastic thyroid cancer, NSUN2 regulates SRSF6 splicing to induce multidrug resistance." (PMID 41399527, 2025). "Furthermore, to elucidate the impact of NSUN2 on anaplastic thyroid cancer (ATC) malignancy, phenotypic assays were conducted." (PMID 37983928, 2023). "In anaplastic thyroid cancer, NSUN2 regulates SRSF6 splicing to enhance UAP1 and ABC transporter function, inducing multidrug resistance reversible by NSUN2 targeting." (PMID 41399527, 2025).
autosomal-recessive intellectual disability (4 papers, 2017 to 2025). "NSUN2 is known to cause forms of autosomal recessive intellectual disability (AR ID) as are methyltransferases from other modification systems, e.g. FTSJ1, a human tRNA 2′-O-methyltransferase, and METTL5, an N6 adenine DNA and rRNA writer." (PMID 39499421, 2025). "Moreover, mutations inside the NSUN2 gene are linked with autosomal-recessive intellectual disability, and overexpression as well as increased copy numbers of NSUN2 have been detected in human cancers." (PMID 29125541, 2017). "Loss-of-function mutations in NOP2/Sun RNA MT2 and MT6 (NSUN2 and NSUN6, respectively) have been identified as the cause of autosomal-recessive intellectual disability (ID) in humans." (PMID 38550277, 2024). "Different studies implicate mutations in NSUN2 in autosomal-recessive intellectual disability, and drosophila mutants lacking the NSUN2 ortholog have severe short-term memory deficits, linking NSUN2 and RNA methylation to cognitive development." (PMID 30477220, 2018).
colitis (4 papers, 2023 to 2026). Inflammation of the colon. "NSUN2 deficiency impairs Th17 polarization and ameliorates colitis, revealing a RORγt-NSUN2 axis that sustains Th17 effector function." (PMID 41424859, 2026). "Nsun2 deficiency in Th17 cells impairs the stability of m5C-modified mRNAs, such as Il17a and Il17f, resulting in ameliorated colitis progression induced by Th17 cells." (PMID 36792629, 2023). "In the mechanism of colitis, RoRγt recruits NSUN2 to the chromatin regions of its target genes, including IL17A and IL17F, leading to the formation of transcription-related m5C and enhancing mRNA stability." (PMID 41462962, 2025). "Collectively, these findings demonstrate that both IL-17A and IL-17F serve as the downstream targets of Nsun2 in Th17 cells and participate in the progression of colitis." (PMID 36792629, 2023). "To explore the functions of m5C in colitis, we generated the DSS-induced and CD45RBhi adoptive transfer colitis models in wild-type and Nsun2-deletion mice." (PMID 36792629, 2023). "To dissect the physiological and pathological functions of Nsun2 in Th17 cells, we induced colitis disease with DSS in Nsun2−/− and wild-type littermates." (PMID 36792629, 2023). "Intriguingly, we found that Nsun2 deletion reduces Th17 cells infiltration in lamina propria of intestinal and mitigates the colitis pathogenesis." (PMID 36792629, 2023). "Here the authors implicate the RNA 5- methylcytosine (m5C) methyltransferase Nsun2 in Th17 cells and the promotion of colitis in a murine model." (PMID 36792629, 2023). "In this study, we demonstrate that Nsun2-mediated m5C modification is crucial for Th17 cell homeostasis and promotes colitis pathogenesis in mice." (PMID 36792629, 2023). "To delineate the dynamics of cell type composition in response to colitis and Nsun2 depletion, we compared the proportion of each cell type among the WT + H2O, WT + DSS, and Nsun2cKO + DSS groups." (PMID 36792629, 2023). "In order to uncover the regulatory pathway of Nsun2 in colitis microenvironment, we applied single-cell RNA-seq analysis with colons from wild-type and Nsun2cKO mice." (PMID 36792629, 2023). "Collectively, these data support that targeting Nsun2 in T cells ameliorates colitis development." (PMID 36792629, 2023). "For example, the proportions of fibroblasts, enterocytes and goblet cells were decreased during colitis and increased upon Nsun2 depletion, indicating that Nsun2-deletion may prevent stromal and epithelial cells from exhaustion during colitis development." (PMID 36792629, 2023). "In contrast, the increases of neutrophils and monocytes in the colitis were also inhibited by Nsun2 depletion, suggesting that Nsun2 may also participates in inflammatory regulation." (PMID 36792629, 2023). "Moreover, we observed that Nsun2-specific deletion in T cells also relieved occurrence of DSS-induced colitis." (PMID 36792629, 2023). "Furthermore, Nsun2 depletion impairs the cell-cell communication between Th17 cells and IL-17 receptor-expressing cell clusters, further restricting the progression of colitis." (PMID 36792629, 2023). "Furthermore, we observed a decreased Th17 cell infiltration in colons of Nsun2cKO mice compared to wild-type mice, indicating that targeting Nsun2 in T cells mitigates the progress of colitis through dampening Th17 cell function." (PMID 36792629, 2023). "Here, we reveal that deletion of RNA 5-methylcytosine (m5C) methyltransferase Nsun2 in mouse CD4+ T cells specifically inhibits Th17 cell differentiation and alleviates Th17 cell-induced colitis pathogenesis." (PMID 36792629, 2023). "Moreover, the T cell specific depletion of Nsun2 could decrease the expression of cytokines, which may lead to the blockage of the cell-cell communication between Th17 cells and IL-17 receptors-expressing cells, further restricting the progression of colitis." (PMID 36792629, 2023).
colitis (continued). "The absence of Nsun2 in mouse CD4+ T cells specifically inhibited Th17 cell differentiation and alleviated colitis caused by Th17 cells." (PMID 41462962, 2025).
hyperhomocysteinemia (4 papers, 2023 to 2025). A serious metabolic condition caused by mutations in the MTHFR gene, medications, or nutritional deficiency. "Nsun2 deficiency significantly alleviated elastase-induced and hyperhomocysteinemia-aggravated mouse abdominal aortic aneurysm." (PMID 41462962, 2025). "NSun2 mediated hyperhomocysteinemia-induced upregulation of IL-17A expression by methylating IL-17A mRNA and promoting its translation in T lymphocytes." (PMID 41462962, 2025). "Nsun2 mediated the development of hypothalamic aortic aneurysm exacerbated by hyperhomocysteinemia by increasing the expression, secretion, and T cell migration of endothelial ATX." (PMID 41462962, 2025). "The m5C methyltransferase NSUN2 mediates the upregulation of interleukin-17a (IL-17A) induced by hyperhomocysteinemia by methylating IL-17A mRNA and enhancing its translation in T lymphocytes." (PMID 39726589, 2024). "In hyperhomocysteinemia, NSUN2 upregulates IL-17A expression by mediating IL-17A mRNA m5C modification in T lymphocytes to induce chronic inflammation." (PMID 37701433, 2023). "Furthermore, Nsun2 methylates Il17a mRNA and promotes its mRNA translation in rat total T lymphocytes upon hyperhomocysteinemia treatment." (PMID 36792629, 2023).
neuroblastoma (4 papers, 2023 to 2025). Neuroblastoma (NB) is the most common solid, extracranial childhood tumor. "Our previous study showed that rs13181449 C > T in the m5C methyltransferase gene NSUN2 confers reduced risk of neuroblastoma." (PMID 37347215, 2023). "Specifically, polymorphisms such as rs3998860 G>A and rs12781492 A>C in the TET1 gene, rs10007915 G>C and rs7670522 A>C in the TET2 gene, rs828867 G>A in the TET3 gene, and rs13181449 C>T in the NSUN2 gene have been identified as closely linked to neuroblastoma susceptibility." (PMID 40984038, 2025). "Importantly, the polymorphism in the NSUN2 gene, rs13181449 C>T, diminishes neuroblastoma susceptibility." (PMID 39744478, 2025).
skin tumours (4 papers, 2020 to 2025). "The finding was further supported by showing that Nsun2 deficient skin tumour initiating cells were more efficiently killed by using chemotherapeutic agents such as 5′ FU or cisplatin, which could be further rescued upon treatment with angiogenin inhibitors." (PMID 33461542, 2021). "Loss of Nsun2 enhances the self-renewal of tumour-initiating cells and contribute to the development or progression of skin tumours, suggesting a potential tumour-suppressive role for Nsun2 in skin cancer." (PMID 39723662, 2025). "Deletion of the m5C methyltransferase NSUN2 results in skin tumor cells being killed more effectively by chemotherapeutic agents such as 5-fluorouracil or cisplatin." (PMID 35309316, 2022). "Regarding tRNA methylation functions, NSUN2 has been reported to be upregulated in a population of proliferative progenitor cells in skin tumours that rely on the correct deposition of m5C onto tRNAs." (PMID 33461542, 2021). "However, paradoxically, in skin cancer, NSUN2 expression was downregulated and the depletion of NSUN2 increased the population of tumor-initiating cells." (PMID 32101138, 2020).
Alzheimer disease (3 papers, 2020 to 2025). A progressive, neurodegenerative disease characterized by loss of function and death of nerve cells in several areas of the brain leading to loss of cognitive function such as memory and language. "Specifically, reduced NSun2 protein expression and an increased pTau/NSun2 ratio have been observed in the brains of Alzheimer’s disease (AD) patients." (PMID 40370440, 2025). "Strikingly, we unravel decreased NSun2 protein expression and an increased ratio of pTau/NSun2 in the brains of patients with Alzheimer’s disease (AD) as demonstrated by Western blotting and immunostaining, respectively." (PMID 36357715, 2023).
atherosclerosis (3 papers, 2022 to 2025). A disease characterized by the build-up of fatty material and calcium deposition in the arterial wall resulting in partial or complete occlusion of the arterial lumen. "Recent research also found NSUN2 play a key role in the progression of atherosclerosis through inflammation." (PMID 40405297, 2025). "Therefore, further research is needed to elucidate the mechanisms by which NSUN2 regulates vascular inflammation and the development of atherosclerosis." (PMID 40370440, 2025). "Additionally, the absence of donor NSUN2 impedes the development of atherosclerosis in a rat model of allogeneic aortic transplantation, suggesting that the NSUN2-ICAM-1 regulatory axis is involved in endothelial cell inflammation." (PMID 40370440, 2025). "As the major mRNA m5C methyltransferase, NSun2 upregulates the expression of ICAM-1 by methylating ICAM-1 mRNA, thereby increasing the adhesion of leukocytes to endothelial cells and contributing to the development of vascular endothelial inflammation and atherosclerosis." (PMID 36093141, 2022).
cholangiocarcinoma (3 papers, 2022 to 2025). A carcinoma that arises from the intrahepatic biliary tree (intrahepatic cholangiocarcinoma) or from the junction, or adjacent to the junction, of the right and left hepatic ducts (hilar cholangiocarcinoma). "In cholangiocarcinoma, the m5C methyltransferase NSUN2 interacts with the lncRNA NKILA to increase its m5C level and promote its interaction with YBX1." (PMID 36333719, 2022).
diffuse large B-cell lymphoma (3 papers, 2025). "In diffuse large B-cell lymphoma (DLBCL) cells, NSUN2 stabilized PDL1 mRNA through an m5C-dependent mechanism and YBX1-dependent pathway." (PMID 41462962, 2025). "In diffuse large B-cell lymphoma (DLBCL), NSUN2 is markedly upregulated in both tissues and cells and can be transferred intercellularly via tumor-derived exosomes." (PMID 41256859, 2025).
glioblastoma (3 papers, 2020 to 2025). The most malignant astrocytic tumor (WHO grade IV). "In glioblastoma (GBM), NSUN2, DNMT3B, NSUN5, TRDMT1, ALKBH1, and HNRNPC were selected." (PMID 40565233, 2025).
stomach cancers (3 papers, 2020 to 2025). "The expression of PTEN was negatively correlated with the expression of NSUN2 in gastric tumor." (PMID 40033337, 2025).